TSLP (thymic stromal lymphopoietin)
Diseases named in the same sentence as TSLP in open-access papers (continued):
Sharing a sentence is not in itself a finding about the gene and the disease.
asthma (continued). "Tezepelumab, an anti-TSLP antibody which regulates Th2 immunity through Th2 and ILC2 cells, has been shown to reduce severe asthma exacerbations, blood eosinophil levels, total serum IgE, and FeNO and to improve FEV1." (PMID 35887589, 2022). "TSLP is crucial for TH2 immunity, which is involved in asthma pathophysiology, as it induces the expression of TH2-associated inflammation drivers, such as IL-4 and IL-5." (PMID 35743783, 2022). "In T2-high asthma, clinical symptoms result from inflammation driven by the cytokines interleukin-4 (IL4), IL5, and IL13, as well as alarmins [thymic stromal lymphopoietin (TSLP), IL25, IL33] and Immunoglobulin E (IgE)." (PMID 36237537, 2022). "In bronchial biopsy tissues, TSLP expression has been shown to colocalize with epithelial CD68+ macrophages in the tissue, with a greater number of macrophages detected in asthma patients compared with control subjects or healthy individuals." (PMID 35572064, 2022). "This is the first approved monoclonal antibody targeting thymic stromal lymphopoietin (TSLP), an epithelial cytokine released by the airway epithelium that acts as early mediator at the top of the allergic inflammatory cascade in asthma." (PMID 36359393, 2022). "In regards to upstream mediators of asthma-like inflammation, HMPV has been shown to induce in vitro expression of IL-33 and TSLP in human alveolar epithelial cells." (PMID 35493465, 2022). "Here we therefore aim to appraise the available evidence for the effect of anti-IgE, anti-IL5 (Rα), anti-IL4Rα, anti-TSLP and anti-IL33 biologics on small airways disease in patients with severe asthma." (PMID 36239786, 2022). "These signals suggest a spectrum of shared genetic influences, some predominantly influencing asthma (FAM105A, GLB1, PHB, TSLP), others predominantly influencing fixed airflow obstruction (IL17RD, C5orf56, HLA-DQB1)." (PMID 35104449, 2022). "However, it is interesting to note that airway hyperresponsiveness to mannitol was significantly more reduced with tezepelumab than with placebo, indicating that anti-TSLP strategy could have additional benefits in asthma beyond reducing type 2 airway inflammation [48▪▪]." (PMID 34608100, 2021). "We previously reported that baicalein inhibits the thymic stromal lymphopoietin (TSLP)/TSLP receptor (TSLPR) signaling pathways and can be used as an active ingredient in the treatment of asthma and atopic dermatitis." (PMID 34575592, 2021). "Alarmins are innate cytokines, including thymic stromal lymphopoietin (TSLP), interleukin-33 (IL-33), and interleukin-25 (IL-25), which are mainly produced by airway epithelium and exert a prominent role in asthma pathobiology." (PMID 34572294, 2021). "Prioritization of druggable genes reveals known (IL4R, TSLP, IL6, TNFSF4) and potentially new therapeutic targets for asthma." (PMID 34103634, 2021). "Thymic stromal lymphopoietin (TSLP) is a cytokine that acts directly on CD4+ T cells and dendritic cells to promote progression of asthma, atopic dermatitis, and allergic inflammation." (PMID 33439121, 2021). "Type 2–high asthma patients had higher miR-206 expression, lower epithelial CD39 expression, elevated BALF ATP levels, and higher epithelial IL-25 and TSLP expression than type 2–low asthma patients." (PMID 33945508, 2021). "Furthermore, filaggrin deficiency could intensify the Th2 responses by induction of inflammatory molecules IL-33 and TSLP under the Th2 condition, which forms a positive feedback regulatory loop to amplify the immune response and promotes the progression of asthma." (PMID 34484176, 2021). "TWAS genes of known biological interest in asthma include IL1RL1 on 2q12, TLR1 on 4p14, TSLP on 5q22, SMAD3 on 15q22-q23, and IL4R on 16p12." (PMID 34103634, 2021). "We found that miR-206, the most highly expressed miRNA in type 2–high asthma relative to type 2–low asthma, targets the CD39–extracelluar ATP axis to regulate IL-25 and TSLP expression in cultured bronchial epithelial cells." (PMID 33945508, 2021).
asthma (continued). "Another promising drug might be Tezepelumab, directed against TSLP, which showed a greater improvement in treated patients as opposed to those with a placebo, but not dramatically enough to be considered statistically significant, and showing a better control of asthma-affected individuals." (PMID 34944487, 2021). "Overview of epithelial cytokines, particularly thymic stromal lymphopoietin (TSLP), released by the airway epithelium and the effects of their inhibition on the outcomes of patients with asthma." (PMID 34608100, 2021). "An impaired skin barrier promotes release of proinflammatory epithelial-derived cytokines, IL-25, IL-33, and thymic stromal lymphopoietin (TSLP), which initiate and propagate Type 2 inflammatory responses in AD, food-hypersensitivity reactions, and asthma." (PMID 33726824, 2021). "Thymic stromal lymphopoietin (TSLP), thymus and activated chemokine (TARC), and IL-8 had also been used in the diagnosis of antifungal treatment of patients with asthma-induced ABPA." (PMID 34621687, 2021). "An inhaled TSLP antibody fragment, CSJ117, has also shown efficacy, and will be tested in a larger phase 2 clinical trial in patients with severe uncontrolled asthma (NCT04410523)." (PMID 33917396, 2021). "Overall, epithelial miR-206 upregulates airway IL-25 and TSLP expression by targeting the CD39–extracellular ATP axis, which represents a potentially novel therapeutic target in type 2–high asthma." (PMID 33945508, 2021). "Some genes such as TSLP, IL-33 and its receptor IL1RL1 have well-established asthma inflammatory roles." (PMID 35386986, 2021). "Other biological therapies studied for treatment of severe asthma with promising results are e.g. pitrakinra (anti-IL 4), dupilumab (anti-IL 4 alpha) and tezepelumab (anti-TSLP; thymic stromal lymphopoietin)." (PMID 32467765, 2020). "Current knowledge suggests that airway epithelial damage triggered by viral infections promotes the production of IL-25, IL-33, and thymic stromal lymphopoietin (TSLP), which in turn leads to the activation of ILC2 and exacerbation of asthma." (PMID 32823491, 2020). "The level of sCD93 which has potential role to predict asthma significantly increased after HDM stimulation via IL-6 and TSLP in vitro and in vivo." (PMID 31941986, 2020). "Thus, the periostin–TSLP axis may be a potential future therapeutic target in asthma." (PMID 33203095, 2020). "Thymic stromal lymphopoietin (TSLP) is a critical upstream cytokine inducing type 2 inflammation in various diseases, including asthma and atopic dermatitis." (PMID 32066836, 2020). "In a double-blind, placebo-controlled study, 31 patients (age range, 8 to 60 years) with mild asthma were randomized to undergo to 3 monthly doses of AMG 157, a human anti-TSLP monoclonal IgG2, or placebo treatment for 12 weeks." (PMID 31355170, 2019). "TSLP is mainly and constitutively produced by epithelial cells of the skin, gut and lungs, and shapes the response of dendritic cells and T cells against invading pathogens in a typical type 2 “weep and sweep” response that when misdirected, may also contribute to asthma and allergic inflammation." (PMID 31921158, 2019). "More recently, in vivo studies have demonstrated that DEHP induces Th2 and Th17 immune responses and airway inflammation in mice, and thymic stromal lymphopoietin (TSLP), Th2 immune response and interleukin-7 receptor in rats; all of which exacerbates asthma." (PMID 31368075, 2019). "A recent study reported that epistasis between TSLP and SPINK5 genes contributes to pediatric asthma." (PMID 29670037, 2018). "Several studies have reported that TSLP promotes production of Th2-related chemokines such as MDC and TARC by mDC and increases disease severity in asthma, atopic dermatitis and T-cell lymphoma." (PMID 28278185, 2017).
asthma (continued). "Type-2 innate lymphoid cells (ILC2s) respond to the cytokines of thymic stromal lymphopoietin (TSLP), interleukin (IL)-25 and IL-33, thus contributing to airway diseases such as CRS and asthma." (PMID 28199345, 2017). "The pro-inflammatory cytokine thymic stromal lymphopoietin (TSLP) plays a pivotal role in the pathophysiology of various allergy disorders that are mediated by type 2 helper T cell (Th2) responses, such as asthma and atopic dermatitis." (PMID 29222519, 2017). "Roles of the cytokines IL-33, thymic stromal lymphopoietin (TSLP) and IL-25 in asthma are receiving considerable interest." (PMID 26879906, 2016). "In this study we demonstrated that HDM-induced experimental asthma involved induction of lung tissue gene expression of four inflammatory cytokines as well as two upstream TH2- cytokines, IL-33 and TSLP." (PMID 26879906, 2016). "Development of TSLP inhibiting therapeutics are underway and currently in phase III clinical trials for asthma and allergy." (PMID 27149122, 2016). "In the present mouse asthma model, the allergen OVA induced the epithelial cells to secrete TSLP, when there was DEHP co-exposure with OVA, the levels of TSLP in pulmonary tissues and BALF were significantly increased." (PMID 27467143, 2016). "We identified that TSLP and CCL11/eotaxin-1 levels were not only significantly elevated in the group with rhinovirus-induced asthma exacerbation, but that their levels had a linear correlation independently of age, gender and ethnicity." (PMID 25546419, 2014). "Thymic stromal lymphopoietin (TSLP), a vital cytokine, plays a critical role in orchestrating, perpetuating and amplifying the inflammatory response in asthma." (PMID 24167583, 2013). "TSLP protein levels are also increased in the airway epithelia and bronchoalveolar lavage fluids (BALF) collected from patients with asthma." (PMID 24167583, 2013). "Thymic stromal lymphopoietin (TSLP), an IL7-like cytokine produced by bronchial epithelial cells is upregulated in asthma and induces dendritic cell maturation supporting a Th2 response." (PMID 21966427, 2011). "The contribution of non-T2 pathways within the T2 asthma endotype is supported by the efficacy of tezepelumab, an anti-TSLP monoclonal antibody, proved to reduce the exacerbations of asthma independent of blood eosinophil counts." (PMID 41602869, 2026). "Thymic stromal lymphopoietin (TSLP) is an epithelial-derived alarmin cytokine that functions as a key upstream orchestrator of both type 2 and non-type 2 inflammatory pathways in asthma pathogenesis." (PMID 42110556, 2026). "In a phase 2 trial of patients with uncontrolled moderate-to-severe asthma randomized to different doses of tezepelumab versus placebo, anti-TSLP therapy reduced asthma exacerbations regardless of high or low blood eosinophil subgroups." (PMID 40863432, 2025). "Two studies reported a weak negative correlation between TSLP concentration and asthma control measured by asthma control test (ACT) in the asthmatic group." (PMID 41357156, 2025). "When we defined Th2 high asthma based on eosinophils count (≥140 cells/μl) and total IgE (IgE >100 IU/ml), the serum TSLP levels were observed higher in subjects experiencing acute exacerbation and persistent asthma compared with no asthma control subjects." (PMID 40503233, 2025). "IL-33 was significantly elevated in females with asthma in comparison to males with asthma, and TSLP levels were not different in the plasma between any of the groups." (PMID 40821845, 2025). "Additionally, FMN reduces the production of cytokines, including thymic stromal lymphopoietin (TSLP), by controlling E-cadherin expression in bronchial epithelial cells, which is crucial for Th2-type inflammation and asthma." (PMID 41199815, 2025). "To date, most experimental studies evaluating TSLP in asthma do not use analytic tools to measure expression of short and long TSLP isoforms separately." (PMID 41357156, 2025).
asthma (continued). "The cytokine TSLP prompts a transformation in airway mast cells, resulting in an increase of a chymotrypsin-positive phenotype observed in asthmatic individuals experiencing AHR, particularly those with severe and uncontrolled asthma." (PMID 40303400, 2025). "Tezepelumab, targeting TSLP, significantly reduced exacerbations in severe asthma but failed to meet endpoints in moderate-to-severe atopic dermatitis." (PMID 41294800, 2025). "Tezepelumab, the first biologic without phenotype and biomarker restrictions for severe asthma, affects airway inflammation via TSLP." (PMID 40486460, 2025). "While TSLP is known to influence allergic diseases like asthma, the role of TSLPR in airway remodeling is not well-defined." (PMID 41259396, 2025). "As such, it is not surprising that the blockade of TSLP has been envisaged as a therapeutic strategy in asthma." (PMID 41145900, 2025). "The WAYPOINT phase 3, randomized, placebo-controlled trial evaluated the efficacy and safety of the anti-TSLP monoclonal antibody tezepelumab in patients with severe CRSwNP, with or without comorbid asthma (NCT04851964)." (PMID 40919679, 2025). "As for the Th2 biomarkers(IL-4 P=0.142, IL-5 P=0.4791, IL-13 P=0.6885, Serum IgE P=0.2534, TARC P=0.2074, TSLP P=0.6571), there are no significant statistical differences observed between asthma and control subjects." (PMID 40503233, 2025). "TSLP > 5.74 cells/mm2 was not a significant predictor for identifying severe MIXED asthma based on our model." (PMID 40022191, 2025). "Tezepelumab is a monoclonal antibody that targets thymic stromal lymphopoietin (TSLP), and it is indicated for severe asthma without phenotype or biomarker limitations." (PMID 39930536, 2025). "A post hoc analysis of the PATHWAY randomized clinical trial (RCT) showed that tezepelumab is effective in reducing exacerbation rates regardless of baseline serum TSLP concentration in patients with severe, uncontrolled asthma." (PMID 41357156, 2025). "The importance of the alarmins, to include TSLP, IL-25 and IL-33, is that they are constitutively expressed by epithelial cells, and once released, activate Th2 cells and ILC2 responses in multiple allergic conditions and asthma." (PMID 40821845, 2025). "We report a case of severe CRSwNP with comorbid severe asthma that showed unfavorable outcomes with DUP treatment but markedly responded to tezepelumab (TEZ), a monoclonal antibody targeting thymic stromal lymphopoietin (TSLP)." (PMID 41409935, 2025). "Treatment with anti-TSLP (tezepelumab) decreased the frequency of asthma exacerbations regardless of the asthma phenotype, including patients with eosinophil-low asthma." (PMID 38255279, 2024). "Studies that integrate the combined effect of TSLP and IL-33 genotypes in relation to circulating cytokine levels and asthma are lacking." (PMID 38731070, 2024). "In conclusion, our findings indicate that in our study, IL-33 and TSLP are not biomarkers of mild asthma in children." (PMID 38731070, 2024). "Initial treatment with a low dose of OCS in combination with tezepelumab, an anti-thymic stromal lymphopoietin (TSLP) antibody, resulted in rapid improvement of asthma and CEP without deteriorating LC." (PMID 38919941, 2024). "Serum IL-33 levels were also elevated in asthma patients, while TSLP showed a non-significant trend." (PMID 38731070, 2024). "Additionally, TSLP can promote airway remodelling through activation of human lung fibroblasts; recent evidence suggests that fibroblasts represent both a source and target of TSLP, which may implicate TSLP as a therapeutic target for airway remodelling in asthma." (PMID 39588080, 2024). "In conclusion, these results suggest that ER stress primes TSLP that is then enhanced further upon TLR3 activation, which may induce severe asthma exacerbations." (PMID 38469627, 2024).
asthma (continued). "Thymic stromal lymphopoietin (TSLP), a cytokine produced primarily by epithelial cells at barrier surfaces and also by dendritic cells, has been studied in the context of asthma." (PMID 39853027, 2024). "Tezepelumab, a human mAb that binds TSLP, has recently been approved for the treatment of patients with severe asthma, with no phenotype or biomarker limitations." (PMID 38609094, 2024). "We did a preliminary study using eosinophils from patients with asthma and found IL-4, IL-13, or TSLP at concentrations up to 10 nM did not induce eosinophil adhesion, O2− generation, or eosinophil degranulation (data not shown)." (PMID 39624446, 2024). "TSLP, a cytokine involved in severe asthma treatment, was never previously studied in non-severe asthma." (PMID 38731070, 2024). "This suggests that anti-TSLP elicits broad inhibitory effects on pathways that are key to inflammation in asthma rather than on narrower inhibition of individual downstream factors." (PMID 38469627, 2024). "Among the various agents used in the treatment of severe asthma, in 2021, the use of Tezepelumab (an anti-TSLP antibody) was approved and has shown promising results in treating severe asthma that is both TH-2 and non-TH-2." (PMID 39057040, 2024). "Moreover, a disrupted airway epithelium drives inflammation in asthma, promoting AHR through the secretion of alarmin cytokines such as thymic stromal lymphopoietin (TSLP), IL-25, and IL-33." (PMID 39199248, 2024). "Tezepelumab is an anti-TSLP human monoclonal antibody that has been shown to reduce the annualized rate of asthma exacerbations compared to the placebo, irrespective of absolute eosinophil counts or other markers of T2 inflammation." (PMID 39194521, 2024). "The TSLP concentration in BALF of those patients was correlated with poor lung function and the dose of corticosteroids used, suggesting that this cytokine is a potential biomarker of severe uncontrolled asthma." (PMID 38469627, 2024). "Initial treatment with a low dose of oral corticosteroids (OCSs) in combination with tezepelumab, an anti-thymic stromal lymphopoietin (TSLP) antibody, resulted in rapid improvement of asthma and CEP without deteriorating LC." (PMID 38919941, 2024). "A similar pattern was observed in the expression profiles of throat Ck8+ epithelial cells in patient samples, with significant increases in TSLP and IL-25 when comparing GINA 5 to all other asthma patients (p < 0.001 and p = 0.003, respectively, after adjusting for age and sex)." (PMID 38999286, 2024). "Despite advances in effective therapeutics against inflammatory cytokines such as Th2 cytokines and TSLP, a significant number of patients with allergic diseases and asthma do not respond to current therapy, highlighting a substantial unmet medical need." (PMID 39160226, 2024). "Mediators including alarmins (IL-25, IL-33, TSLP) and OX40L have overlap between T2 and non-T2 inflammation and may signify unique pathways of asthma inflammation." (PMID 39194521, 2024). "While PM of greater than 2.5 μm (PM2.5–PM10 and PM10) has important clinical implications for asthma patients, its effects on TSLP release have not been studied." (PMID 38672419, 2024). "Since TSLP acts on the early upstream of the inflammatory cascade, SHR-1905 may be suitable for a wide range of patients with severe uncontrolled asthma, potentially including those with non-T2-driven asthma." (PMID 39076593, 2024). "To date, the United States Food and Drug Administration (FDA) has approved six biologics for use in selected severe asthma patients: Omalizumab (anti-IgE); Mepolizumab, Benralizumab, Reslizumab (anti-IL5/anti-IL5Rα); Dupilumab (anti-IL4Rα); and Tezepelumab (anti-TSLP)." (PMID 38259298, 2023). "Additionally, RV infection increased mRNA expression and protein secretion of thymic stromal lymphopoietin (TSLP) from epithelium of controls and patients with asthma." (PMID 37087523, 2023).